RNU6-752P (RNA, U6 small nuclear 752, pseudogene)
Gene: Small nuclear RNA gene on chromosome 5 (126,755,316 to 126,755,417, reverse strand). Ensembl gene ENSG00000252185.
Homologues: Orthologues: chimpanzee U6 (98% identical), macaque U6 (92% identical), mouse Gm25524 (85% identical), dog U6 (72% identical). Paralogues in human: RNU6-797P (84% identical), RNU6-1094P (83% identical), RNU6-1243P (83% identical), RNU6-1287P (83% identical), RNU6-944P (83% identical), RNU6-1083P (82% identical), RNU6-1091P (82% identical), RNU6-655P (82% identical), RNU6-115P (81% identical), RNU6-1249P (81% identical), RNU6-196P (81% identical), RNU6-379P (81% identical), and 1283 more.